MYCN (MYCN proto-oncogene, bHLH transcription factor)
Diseases named in the same sentence as MYCN in open-access papers (continued):
Sharing a sentence is not in itself a finding about the gene and the disease.
Wilms tumor (40 papers, 2011 to 2025). An embryonal neoplasm characterized by the presence of epithelial, mesenchymal, and blastema components. "Wilms tumor contributes around 6% to overall childhood neoplasms and shows mutations in MYCN along with copy number gains and overexpression." (PMID 37046804, 2023). "MYCN amplification and mutation (P44L) are among the most frequent recurrent genetic alterations in anaplastic Wilms tumor." (PMID 35406427, 2022). "Overexpression of the P44L mutant N-MYC (most common MYCN mutation found in Wilms tumor) was associated with increased TERT promoter luciferase activity and TERT expression relative to wild type MYCN." (PMID 35406427, 2022). "High MYCN expression has also been associated with high-risk Wilms tumor as defined by post-treatment anaplasia or blastemal histology WT." (PMID 35406427, 2022). "In this study, we investigated the association between MYCN gene polymorphisms and Wilms tumor susceptibility." (PMID 31343784, 2019). "Our study is the first investigation to explore the relationship of MYCN gene SNPs with Wilms tumor susceptibility." (PMID 31343784, 2019). "The association between other MYCN polymorphisms and Wilms tumor susceptibility should be further explored." (PMID 31343784, 2019). "Adjusted odds ratios (AORs) and 95% confidence intervals (CIs) were calculated to evaluate the association between MYCN gene polymorphisms and Wilms tumor susceptibility." (PMID 31343784, 2019). "We performed the current study to investigate the association of MYCN gene polymorphisms with Wilms tumor risk." (PMID 31343784, 2019). "Here we present a comprehensive copy number analysis of MYCN in Wilms tumour (WT), demonstrating that gain of this gene is associated with anaplasia and with poorer relapse-free and overall survival, independent of histology." (PMID 25749049, 2015). "•MYCN gain or mutation as a promising target for treating high risk Wilms tumors." (PMID 39740515, 2025). "In addition to copy number gain, MYCN was also found to contain activating point mutation in Wilms tumor." (PMID 37046804, 2023). "For Wilms tumors, 1q and MYCN gains, as well as 17p loss, were correlated with a poor outcome." (PMID 37189699, 2023). "Gene expression and DNA analyses have also demonstrated overexpression of MYCN mRNA, as well as focal amplifications, copy number gains and presumptive change of function mutations of MYCN in Wilms’ tumours with poorer outcomes, including tumours with diffuse anaplasia." (PMID 33562123, 2021). "However, stratification and haplotype analyses revealed the potential contribution of MYCN polymorphisms to Wilms tumor risk." (PMID 31343784, 2019). "Our study demonstrated that these MYCN gene polymorphisms might be low penetrant variants in Wilms tumor." (PMID 31343784, 2019). "Thus, we conducted this study to identify the association between MYCN SNPs and Wilms tumor susceptibility." (PMID 31343784, 2019). "Here we report the discovery of MYCN P44L mutations through whole exome analysis of Wilms tumour, leading us to hypothesise that multiple routes to MYCN-oncogenesis may exist in this paediatric tumour." (PMID 25749049, 2015). "Additionally, MYCN amplification and mutation (gain-of-function P44L hotspot mutation) are suspected to contribute to the pathogenesis of anaplastic WT and are among the most common genetic alterations found in Wilms tumor." (PMID 35406427, 2022). "In subject 2, a Wilms tumor; there were less oncogenic events, and ASXL1 S577* hotspot mutation was shared across all whereas MYCN P44L was present in later biopsies." (PMID 38347552, 2024). "In the current study, we found an association between MYCN amplification and the P44L MYCN mutation and increased TERT expression in Wilms tumor xenografts and primary tumor specimens." (PMID 35406427, 2022). "Together, our study identifies regulatory axes that interact with MYCN, providing novel pathways for potential targeted therapeutics for poor-prognosis Wilms’ tumour." (PMID 33562123, 2021).
Wilms tumor (continued). "Surprisingly, however, the expression and functions of the MYCN protein in Wilms’ tumours still remain obscure." (PMID 33562123, 2021). "Especially MYCN and PEG10 showed very similar patterns of expression in different subtypes of Wilms tumors, predominantly the high-risk blastemal type, where YEATS2 was also significantly overexpressed." (PMID 34689785, 2021). "In this study, we assessed MYCN protein expression in primary Wilms’ tumours using immunohistochemistry of tissue microarrays." (PMID 33562123, 2021). "Five of seven proven candidates, PEG10, YEATS2, FOXK1, CBLL1 and MCRS1 showed a clear positive correlation of mRNA levels with MYCN in Wilms tumors undergoing the SIOP protocol." (PMID 34689785, 2021). "For functional studies, we used two anaplastic Wilms’ tumour cell-lines, WiT49 and 17.94, to study the biological and transcriptomic effects of MYCN depletion." (PMID 33562123, 2021). "In total MYCN alterations affected up to 18.5% of Wilms tumors treated with preoperative chemotherapy, suggesting an important oncogenic function of MYCN." (PMID 34689785, 2021). "Copy number gains that include the MYCN locus are detected in 12.7% of Wilms tumors and 30.4% of diffuse anaplastic Wilms tumors, and MYCN gain is associated with poorer relapse-free and overall survival." (PMID 33628735, 2020). "Our results suggest a significant role for MYCN dysregulation in the molecular biology of Wilms tumour." (PMID 25749049, 2015). "The results presented here suggest that MYCN function in Wilms tumour is potentiated by several mechanisms." (PMID 25749049, 2015). "MYCN gain was measured in 293 WT cases using the P380 Wilms Tumour probemix (gain threshold = 1.2, determined empirically with reference to Affymetrix and Illumina SNP array data)." (PMID 25749049, 2015). "This spliceosomal vulnerability likely extends to other components of the spliceosomal machinery such as HNRNPA1, RBM39 and SNRPD3, as well as other cancers such as Wilms’ tumour, where our transcriptomic analyses revealed MYCN regulation of spliceosome regulators including SNRPD1 and WDR77." (PMID 39313128, 2024). "Several groups have explored the influence of MYCN gene on Wilms tumor." (PMID 31343784, 2019). "However, the role of active MYCN in regulating metabolic enzymes and maintaining the “stemness” of cells in Wilms tumor is still unknown." (PMID 39802403, 2025). "MYCN overexpression is also observed in other nervous system tumors such as medulloblastoma, glioblastoma, retinoblastoma, and spinal ependymoma, as well as tumors outside of the nervous system such as neuroendocrine prostate cancer, nephroblastoma (Wilms’ tumor), and many others." (PMID 34625907, 2022). "However, the role of MYCN remained unclarified in Wilms tumor." (PMID 31343784, 2019). "Extended expression analysis in our own independent cohort of 299 Wilms tumors by qRT-PCR confirmed the correlated expression of PEG10 and YEATS2 with MYCN." (PMID 34689785, 2021). "MYCN, a key driver of several pediatric tumors and a prominent negative prognostic marker in Wilms tumors, showed differential expression, with elevated levels in compact organoids." (PMID 39740515, 2025). "Consistently, only a weak positive correlation of MYCN expression with copy number is detected in Wilms tumor, while a strong negative correlation of MYCN expression with DNA methylation level at specific loci is observed." (PMID 33614505, 2020). "MYCN was not amplified to serve as an important criterion of distinction between neuro- and nephroblastoma." (PMID 28818093, 2017). "Overexpression of MYCN is common in Wilms’ tumor even in the absence of increased copy number of the gene." (PMID 28358317, 2017).
ependymoma (37 papers, 2019 to 2025). A WHO grade II, slow growing tumor of children and young adults, usually located intraventricularly. "For example, the identification of MYCN amplification in spinal ependymoma or H3 K27M mutations in astrocytoma can guide clinicians toward more aggressive surveillance and treatment plans, even when traditional features suggest a low-grade lesion." (PMID 41154124, 2025). "Molecular typing of pediatric spinal ependymomas aids in identifying very high-risk MYCN-amplified ependymomas." (PMID 39713042, 2024). "While spine ependymomas (including those with NF2 mutation) are, in general, regarded as good prognosis, MYCN-amplified spinal ependymomas in particular exhibit aggressive behavior, rapid progression, early metastases, and leptomeningeal dissemination." (PMID 41154124, 2025). "Recent studies have identified MYCN amplification as a key driver of aggressive spinal ependymomas in pediatric patients." (PMID 40365336, 2025). "MYCN-amplified ependymomas for example, are aggressive tumors, with an increased likelihood of recurrence and metastasis, and often have leptomeningeal metastases at presentation." (PMID 38902483, 2024). "Since then, several of these molecular types have been further divided into subtypes, and the MYCN-driven spinal ependymomas have been identified as an additional tenth type of ependymoma." (PMID 38265522, 2024). "Unsupervised analysis of spinal ependymal tumors revealed a similarity of the described samples with proteome patterns of spinal MYCN-amplified ependymomas but clear distances from spinal ependymomas and subependymomas." (PMID 38735021, 2024). "Myxopapillary ependymoma (SP-MPE, n = 32, 63%) was the most common molecular type followed by spinal ependymoma (SP-EPN, n = 17, 33%) and MYCN-amplified ependymoma (n = 2, 4%)." (PMID 39713042, 2024). "Ependymomas located inside the spinal canal were classified into two subtypes- spinal ependymoma, and spinal ependymoma, MYCN-amplified (SP-EPN-MYCN)." (PMID 36824145, 2023). "In spinal ependymomas, there is a new group defined by MYCN amplification, which indicates a more aggressive tumor." (PMID 37287627, 2023). "While ependymomas often have similar histologic features regardless of location, their molecular alterations are distinct with ZFTA and YAP1 fusions seen in supratentorial ependymomas and MYCN amplification in a subset of spinal ependymomas." (PMID 36969278, 2023). "Histologically, ependymomas with MYCN amplification present with characteristic ependymal features and signs of anaplasia." (PMID 34008056, 2021). "Using a similar DNA methylation assay, two other studies recorded similar results, leading to a total of 27 published cases of ependymoma with MYCN amplification, which has led to the categorization of this subset of SPE." (PMID 34944845, 2021). "In this study, we identified and characterized a novel molecular subgroup of spinal ependymoma designated as SP-EPN-MYCN with histological features of ependymoma and a characteristic MYCN amplification." (PMID 31414211, 2019). "We, therefore, propose to establish SP-EPN-MYCN as a new molecular subgroup in ependymoma and advocate for testing newly diagnosed spinal ependymal tumors for MYCN amplification." (PMID 31414211, 2019). "Taking these findings into account, we suggest to designate this molecular subgroup spinal ependymoma with MYCN amplification, SP-EPN-MYCN." (PMID 31414211, 2019). "Based on the fifth edition (2021) of the World Health Organization (WHO) classification of central nervous system tumors, spinal cord ependymal tumors encompass 4 histological types: ependymoma (grade II), subependymoma (grade I), myxopapillary ependymoma (grade II), and MYCN-amplified ependymoma." (PMID 39792750, 2025). "While the posterior Fossa (PF) ependymomas are denominated into PFA and PFB depending on methylation profiles, spinal ependymomas may show MYCN amplification." (PMID 40677455, 2025).
ependymoma (continued). "It plays a role in the pathogenesis of several tumors, such as medulloblastoma and neuroblastoma, but the mechanisms involving MYCN in ependymomas development are still unknown." (PMID 38544524, 2024). "While amplifications of MYCN therefore need to be investigated specifically, global DNA methylation profiling has emerged as an extremely valuable tool to classify tumors of the central nervous system in general and ependymomas specifically." (PMID 38735021, 2024). "Anyway, immunohistochemistry for MYCN may be a useful screening method in spinal ependymomas showing suspicious clinico-radiological and histopathological features, but the amplification should always be demonstrated by molecular analyses, such as FISH." (PMID 38544524, 2024). "This also indicates that overexpression of MYCN in hGFAP-positive cells is not sufficient to drive MYCN-associated ependymoma that were recently described in humans." (PMID 37608807, 2023). "SP-EPN with MYCN amplification has been recently proposed as a new ependymoma subgroup." (PMID 34041479, 2021). "This new classification includes supratentorial ZFTA-fusion-positive ependymoma, supratentorial YAP1-fusion-positive ependymoma, posterior fossa ependymomas groups PFA and PFB, spinal ependymoma, and MYCN-amplified spinal ependymoma." (PMID 40864821, 2025). "The ependymomas are classified on the basis of specific gene alterations, such as ZFTA or YAP1 fusions being characteristic in supratentorial ependymomas, and MYCN amplification being the norm in spinal ependymomas." (PMID 40677455, 2025). "For the group of MYCN-amplified spinal (EPN-MYCN) and the YAP1-fusion positive (EPN-YAP) ependymoma, 17 tumors were identified for each group." (PMID 38265522, 2024). "Improved PFS following ependymoma resection has been associated with a number of other tumor specific characteristics including lower Ki-67%, lower tumor grade, Vimentin negative tumors, absence of MYCN amplification, and an identifiable tumor plane intraoperatively." (PMID 38438766, 2024). "Apart from the well-known subependymomas (CNS WHO grade 1), ependymomas, and myxopapillary ependymomas (both CNS WHO grade 2), spinal ependymomas with MYCN amplification have more recently been identified as the most aggressive type of spinal ependymoma." (PMID 38735021, 2024). "Among them inverse correlations (r > −0.61) were noted in the ependymoma group for miR-106b-MYCC, miR-106b-MYCN, miR-106b-E2F2, miR-106b-E2F3, miR-93-MYCN, miR-25-MYCN, miR-25-E2F2, miR-25-E2F3, i.e., members of the miR-106b-25 cluster." (PMID 33430425, 2021). "We found that ependymoma tissues and lines express BET proteins and their targets MYC and MYCN." (PMID 33668642, 2021). "Six cases were stained retrospectively for MYCN protein and all showed strong overexpression, while 6 classic Grade II spinal cord ependymomas were negative for MYCN protein expression." (PMID 32641156, 2020). "We stained 20 spinal ependymomas without MYCN amplification, 10 of the methylation group SP-EPN and 10 of the methylation group SP-MPE." (PMID 31414211, 2019). "One non-myxopapillary grade 2 ependymoma had an MYCN amplification." (PMID 39713042, 2024). "Notably, a recent report described a case of a spinal ependymoma, with poor clinical outcome and DNA methylation profile consistent with ependymoma MYCN-amplified, lacking MYCN amplification and rather harboring MYC amplification." (PMID 38074692, 2023). "In ependymomas, gene expression negatively correlated with the expression of cluster members, e.g., miR-106b-MYCC r = −0.42, miR-106b-MYCN r = −0.61, miR-106b-E2F2 r = −0.51, miR-106b-E2F3 r = −0.58, miR-93-MYCN r = −0.47, miR-25-MYCN r = −0.47, miR-25-E2F2 r = −0.49, miR-25-E2F3 r = −0.52." (PMID 33430425, 2021).
ependymoma (continued). "Methylation array analysis revealed that none of the eight MYCN amplified cases could be confidently classified within any of the 9 known ependymoma methylation subgroups, including those from the posterior fossa and the supratentorial region." (PMID 32641156, 2020). "None of 16 grade II spinal ependymomas or 26 classic ependymomas from the posterior fossa or a supratentorial location (14 Grade III EPN, 12 Grade II EPN) that were profiled in our laboratory displayed MYCN amplification." (PMID 32641156, 2020).
brain tumors (36 papers, 2010 to 2025). "We conclude that combined loss of CREBBP and overexpression of MYCN in NSCs induces brain tumor formation with early postnatal manifestation and specific location in the OB." (PMID 37407554, 2023). "Our work is based on the analysis of pediatric infratentorial brain tumors, and a high level of MYCN expression can be associated with the development of the cerebellum." (PMID 33430425, 2021). "Brain tumors with H3F3A G34 mutations have been associated with an increased expression of MYCN, another transcription factor well known for its oncogenic capacity." (PMID 28484590, 2017). "MYC and MYCN have been found to have specific and different Arf suppression mechanisms and effects in brain tumors and amplifications are associated with different tumor groups in brain tumors." (PMID 37533331, 2023). "MYCN is a proto-oncogene that is amplified in various types of cancers, particularly pediatric brain tumors, which are the primary focus of this review." (PMID 40365336, 2025). "Completed interventional clinical trials focusing on targeting regulation pathways of MYCN in pediatric brain tumors." (PMID 40365336, 2025). "This review explores the role of MYCN in different subtypes of pediatric brain tumors and highlights novel ongoing therapeutic approaches." (PMID 40365336, 2025). "Beyond NB, MYCN amplification is also observed in pediatric brain tumors, including pediatric high-grade gliomas (pHGGs) and MBs with SHH, Group 3, and Group 4 subtypes." (PMID 41228232, 2025). "The reduction of MYCN protein levels in MYCN-driven brain tumors is of major importance due to its central role as an oncogenic driver." (PMID 41211440, 2025). "CREBBP is a tumor suppressor, whose decreased expression cooperates with the oncogene MYCN to induce malignant brain tumors in mice." (PMID 39043735, 2024). "We and others have discussed the potential benefits of the CDK4/6 inhibitors palbociclib, ribociclib, and abemaciclib in the context of MYCN-driven MB and other brain tumors." (PMID 38730706, 2024). "Overexpression of the MYCN gene is a characteristic feature of many embryonal brain tumors, leading to enhanced cell proliferation and cell cycle disruption." (PMID 39239553, 2024). "Compared to MYCN-expressing brain tumors driven from the same promoter, pronounced ARF silencing is present in our MYC-expressing model and in human MB." (PMID 38730706, 2024). "MYCN directly inhibits p5326 but it is less clear if MYCN can modulate ARF activity during brain tumor development." (PMID 36869047, 2023). "The respective penetrance of brain tumors and neuroendocrine tumors in both MYCN-based models (hGFAP-cre::CrebbpFl/Fl::lsl-MYCN and hGFAP-cre::lsl-MYCN) was most likely dependent on MYCN dosage." (PMID 37407554, 2023). "We observed MYCN amplification in one tumor, which was predicted to be a “Plexus Tumor” by the Heidelberg brain tumor classifier." (PMID 34041479, 2021). "The dual role of CDK2 in MYCN-driven brain tumors was shown to successfully target MYCN-driven MB in 2018." (PMID 33585252, 2020). "We will also portray current treatment regimens and patient outcomes and reflect on how targeted treatments of MYCN would improve future therapies for the most common and aggressive types of brain tumors." (PMID 33585252, 2020). "Several mTOR inhibitors have already been approved or are currently undergoing clinical trials, making mTOR inhibition a very promising therapeutic avenue for MYCN-deregulated brain tumors." (PMID 33585252, 2020). "RapaLink-1, a bivalent third generation mTOR inhibitor, which combines rapamycin with INK128 (Sapanisertib) by an inert chemical linker, has also shown great efficacy in MYCN-driven brain tumor models." (PMID 33585252, 2020).